HLA-B (major histocompatibility complex, class I, B)
Diseases named in the same sentence as HLA-B in open-access papers (continued):
Sharing a sentence is not in itself a finding about the gene and the disease.
thyroid nodule (3 papers, 2019 to 2023). A small circumscribed mass in the THYROID GLAND that can be of neoplastic growth or non-neoplastic abnormality. "Most of the patients with HLA-B*18:01 alone had a unilateral, homogenously hypoechoic single SAT region that filled the entire affected lobe and resembled a large thyroid nodule." (PMID 37008914, 2023). "In patients with co-presence of HLA-B*18:01 and -B*35, the main difference from the typical pattern concerned the shape of the SAT lesions, which were patchy or round, imitating actual thyroid nodule." (PMID 33950404, 2021). "In most cases with HLA-B*18:01 only, unilateral homogenously hypoechoic single SAT area, filling the whole affected lobe and mimicking the large thyroid nodule was observed." (PMID 33950404, 2021). "In most cases with HLA-B*18:01 only, there was unilateral homogenously hypoechoic single SAT area, which filled the whole affected lobe, mimicking the large thyroid nodule." (PMID 30728805, 2019).
thyrotoxicosis (3 papers, 2019 to 2023). A hypermetabolic syndrome caused by the elevation of thyroid hormone levels in the serum. "The authors of the subsequent articles regarding the significance of HLA-B*35 in SAT used RAIU in the diagnosis of the disease, or the diagnosis was based only on the clinical presentation, elevated ESR and laboratory features of thyrotoxicosis." (PMID 30728805, 2019).
Type 2 Diabetes (3 papers, 2019 to 2021). "This study has found deleterious mutations in human leukocyte antigen-B (HLA-B) gene associated with type 2 diabetes in Pashtun ethnic population of Khyber Pakhtunkhwa, Pakistan, using high-throughput sequencing." (PMID 34258292, 2021). "So far, five African-American type 2 diabetes-associated signals have been reported, three of which (two in KCNQ1 and one in HMGA2) were first reported in Europeans and two (INS-IGF2 and HLA-B) were first reported in African-Americans." (PMID 31049640, 2019).
vasculitis (3 papers, 2015 to 2023). "Although the involvement of class I HLA genes in Kawasaki disease (a vasculitis involving medium-sized blood vessels) is controversial, HLA-B*51 and HLA-B*44 have been proposed to be associated with this disease." (PMID 25889603, 2015). "The connective tissue presented an intense mixed inflammatory infiltrate, congested blood vessels, haemorrhage, vasculitis, and HLA-B genotyping identified the expression of HLA-B15, further supporting the BD diagnosis." (PMID 37509521, 2023). "However, in contrast to previous studies, we could not confirm an association between HLA-B alleles and renal manifestations or any other specific features of this vasculitis." (PMID 25889603, 2015).
Achalasia (2 papers, 2018 to 2023). A disorder of esophageal motility characterized by the inability of the lower esophageal sphincter to relax during swallowing and by inadequate or lacking peristalsis in the lower half of the body of the esophagus. "For the HLA-B locus, the most common alleles in achalasia patients were B*39:05, B*35:01 and B*44:03, with gene frequencies of 0.0989, 0.0549 and 0.0495, respectively." (PMID 30092016, 2018). "HLA-B and HLA-DRB, differentially expressed in C1QC+ macrophages or TRM, were risk genes for both achalasia and MS (, b)." (PMID 37542039, 2023). "Admixture estimations using HLA-B as the genetic estimator revealed that among the patients with achalasia, 56.7% of their genes were of Native American descent, 24.7% were of European descent, 16.5% were of African descent and 2.0% were of Asian descent." (PMID 30092016, 2018). "HLA-B/-C/-DRB1/-DQB1 conserved extended haplotypes in achalasia patients and healthy controls." (PMID 30092016, 2018).
alveolar rhabdomyosarcoma (2 papers, 2023). A rapidly growing malignant mesenchymal neoplasm. "Furthermore, no HLA-A and only a single HLA-B or -C allele was detected from RNA-Seq of two rhabdomyosarcoma PDXs (GR-RMS-2 and -10), and single HLA-B and -C alleles were detected in two others (GR-RMS-1 and -11)." (PMID 38318504, 2023).
aplastic anemia (2 papers, 2019 to 2024). Anemia resulting from bone marrow failure (aplastic or hypoplastic bone marrow). "Previous studies have demonstrated an association between HLA-B*40:02 and acquired aplastic anemia, where the auto-antigen presentation caused a T-cell-mediated cytotoxicity, and in consequence, allele-expressing CD34+ cells were eliminated." (PMID 31575081, 2019). "While the literature lacks extensive documentation on the relationship between HLA-B*49:01:01 and CLL, as noted in the context of its association with CD22, this particular allele appears to serve as a promising marker for aplastic anemia." (PMID 39329950, 2024).
atherosclerosis (2 papers, 2023 to 2024). A disease characterized by the build-up of fatty material and calcium deposition in the arterial wall resulting in partial or complete occlusion of the arterial lumen. "Within MHC-I, alleles for HLA-B*13:02 and HLA-C*06:02 were associated with a higher atherosclerotic burden while HLA-B*38:01 was associated with less atherosclerosis when researchers adjusted for other cardiovascular risk factors in patients with psoriatic disease." (PMID 37681883, 2023).
autoimmune encephalitis (2 papers, 2020 to 2022). Inflammation of the brain secondary to an immune response triggered by the body itself. "After Bonferroni correction, HLA‐B*27:05 was significantly associated with autoimmune encephalitis by atezolizumab (corrected P < 0.001, odds ratio 59, 95% CI = 9.0 ~ 386.9)." (PMID 33031633, 2020). "Here we found that three in five patients with autoimmune encephalitis associated with atezolizumab had the rare HLA‐B*27:05 genotype." (PMID 33031633, 2020).
breast tumor (2 papers, 2023 to 2024). "We observed distinct patterns of methylation across the HLA genes in the LUAD, LUSC and breast tumors, with the gene body having the highest methylation in HLA-A and HLA-B in both tumor and normal tissues." (PMID 39358601, 2024).
cervical (2 papers, 2012 to 2017). "Additionally, we demonstrated a potential association of a HLA class I haplotype (HLA-B*14-C*08) with higher IL-10 cytokine serum levels in cervical disease, suggesting an association between HLA class I and specific cytokines in cervical carcinogenesis." (PMID 28858203, 2017). "This was positively correlated with the downregulation of corresponding gene transcription, in addition to HLA-A, HLA-B and HLA-C genes coding for HLA-I, in fresh cervical lesions detected by semi-quantitative RT-PCR." (PMID 23024775, 2012).
Chagas disease (2 papers, 2012 to 2025). A parasitic infection caused by Trypanosoma cruzi. "On the other hand, HLA-B*39:01 has been associated with susceptibility and development of the symptomatic form of Chagas disease." (PMID 40333154, 2025).
chickenpox (2 papers, 2017 to 2021). A contagious childhood disorder caused by the varicella zoster virus. "We identified independent associations of adults with a history of chickenpox with HLA-A and HLA-B in the class I region." (PMID 28928442, 2017).
chronic hepatitis C (2 papers, 2015 to 2021). "The factors analyzed in our previous study using conventional univariate and multivariate analysis showed that there was a strong association between IFNL3, HLA-B*44, KIR3DS1, and HLA-C*12 and the probability of developing chronic hepatitis C." (PMID 33624609, 2021). "In our previous study, we proposed a simple tool for the prediction of spontaneous resolution and chronic hepatitis C based on IFNL3 genotype and genetic profiles (GUP/GFP) using a combination of HLA-B, HLA-C, and KIR genes." (PMID 33624609, 2021).
cognitive decline (2 papers, 2022 to 2024). "Indeed, HLA-B*4402 affects both brain atrophy and cognitive decline and is linked to potential AD risk and had interaction causing altered brain volume in non-Hispanic Caucasians, while HLA-B7, a HLA-B serotype, is associated with AD in Caucasian populations." (PMID 35883662, 2022).
colitis (2 papers, 2022 to 2023). Inflammation of the colon. "In this study, SR‐B1 deficiency controlled the TAM, M‐MDSCs and G‐MDSCs and PD‐L1 level and increased the level of HLA‐B in the intestine of the colitis‐induced CRC mice." (PMID 37766594, 2023). "A positive correlation between IRAE and homozygosity was found for HLA-A and HLA-C homozygosity for colitis, and HLA-A, HLA-B, and HLA-C homozygosity for hepatitis." (PMID 35053465, 2022). "HLA-B homozygosity is seemingly a protective factor in general IRAE, colitis or pancreatitis." (PMID 35053465, 2022).
cutaneous leishmaniasis (2 papers, 2013 to 2016). Leishmaniasis affecting the skin. "Overall, several of the alleles in the HLA-B region which have been associated with susceptibility or protection towards cutaneous leishmaniasis in other populations, were also shown to differ between patients and controls of our study group." (PMID 27301744, 2016). "We studied the association of variations at HLA class I (HLA-A, HLA-B) and HLA class II (HLA-DRB1, HLA-DQB1) loci with susceptibility to localised cutaneous leishmaniasis in Sinhalese in Sri Lanka." (PMID 27301744, 2016). "Allele frequency of HLA-DRB1*13 (P = 0.0228, Pc = 0.3317) was conspicuous only in the non-recurrent cutaneous leishmaniasis groups, whereas HLA-B*49 was prominent in the recurrent disease group." (PMID 23638805, 2013).
delayed hypersensitivity reactions (2 papers, 2017 to 2023). "For carbamazepine-induced delayed hypersensitivity reactions, the most powerful association has been established with HLA-B*15:02 as a genetic risk factor in developing SJS/TEN in Han Chinese, Thai, Indian, and Malaysian populations." (PMID 37628756, 2023).
dermatitis (2 papers, 2011 to 2024). An inflammatory process affecting the skin. "Moreover, a study on the HLA gene locus variation in specific dermatitis found that the HLA-B residue of 80 (T-threonine) is related to the remission of AD." (PMID 38378549, 2024).
diffuse large B-cell lymphoma (2 papers, 2023 to 2024). "While risk of diffuse large B-cell lymphoma and marginal zone lymphoma were increased with homozygosity of class I HLA-B and HLA-C loci and the class-II HLA-DRB1 locus, follicular lymphoma risk was associated with the increase in homozygous loci for HLA class II genes." (PMID 37942321, 2023). "Previous studies mention the predisposing role of HLA-B*08:01, HLA-DRB1*03:01, and HLA-DRB1*09 alleles in the case of diffuse large B-cell lymphoma." (PMID 38535155, 2024).
dilated cardiomyopathy (2 papers, 2023 to 2024). Cardiomyopathy which is characterized by dilation and contractile dysfunction of the left and right ventricles. "The enrichment results of the KEGG analysis for the HLA-B low-expression group were enriched in “dilated cardiomyopathy” and “hypertrophic cardiomyopathy (HCM)”." (PMID 38728374, 2024).
Ebola (2 papers, 2024 to 2025). "It is interesting to note that for HLA-B the largest values overall are obtained for Ebola NP (Sudan)." (PMID 39624092, 2024). "Correspondingly, antigen presentation ISGs (HLA-B, PSMB8, PSMB9, and TAP1102) were not markedly induced by Ebola, although they were upregulated in response to other viruses." (PMID 41279810, 2025).
encephalitis (2 papers, 2021 to 2024). An acute inflammatory process affecting the brain parenchyma. "In our case–control study, we found one case of HLA-B*1502 gene-negative AED-MPE: the patient was a 60-year-old male with a history of “viral encephalitis” in May 2018." (PMID 34488672, 2021).
gastric cancer (2 papers, 2021 to 2025). A primary or metastatic malignant neoplasm involving the stomach. "Therefore, both HLA-B alleles and MICA*009/049 could to be factor risk in gastric cancer, so we suggest to consider this information for future studies." (PMID 33868281, 2021).
giant cell arteritis (2 papers, 2015 to 2024). "An association of HLA-B*15, HLA-B*8, HLA-Cw3 and HLA-Cw6 with giant cell arteritis (a large-sized blood vessel vasculitis) has been reported." (PMID 25889603, 2015). "It should be noted that the presence of threonine at position 45 of HLA-B was previously identified as an independent HLA signal in giant cell arteritis;4 however, the linkage disequilibrium between threonine at position 45 of HLA-B and the SNP identified in the present study was low (r2 0·15)." (PMID 38734017, 2024).
glioblastoma (2 papers, 2009 to 2025). The most malignant astrocytic tumor (WHO grade IV). "In a previous study, several HLA-B and HLA-C alleles and haplotypes were positively or negatively associated with the occurrence and prognosis of glioblastoma multiforme (GBM)." (PMID 19774073, 2009).
hantavirus pulmonary syndrome (2 papers, 2012 to 2018). An infection caused by Hantaviruses. "Individuals with HLA-B*3501 have an increased risk of developing severe Hantavirus pulmonary syndrome (HPS), and have significantly higher frequencies of SNV-specific HLA-B*3501 restricted T cells." (PMID 29914514, 2018).
Hashimoto disease (2 papers, 2010 to 2021). "Neither HLA-C nor HLA-B*27 alleles have been implicated in the development of Hashimoto's thyroiditis; thus, evidence regarding an HLA link for psoriasis with Hashimoto's thyroiditis has not been fully elucidated." (PMID 33585138, 2021).
hemorrhagic fever (2 papers, 2010 to 2022). An infectious disease caused by certain viruses or bacteria that can damage the walls of tiny blood vessels, making them leak, and can hamper the blood's ability to clot and cause severe, life-threatening illness. "The involvement of HLA-B*51-restricted CTL responses to a variety of viruses have been reported, including for Hantaan virus which also causes a hemorrhagic fever." (PMID 20927388, 2010).
Hepatic fibrosis (2 papers, 2015 to 2020). The presence of excessive fibrous connective tissue in the liver. "We encountered several limitations while performing this work such as the low number of HLA‐B*57 typed patients, responsible for the loss of statistical power in multivariate analysis and that we were unable to include data on IL28B genotype and liver fibrosis." (PMID 32909370, 2020).
Hepatitis (2 papers, 2015 to 2022). Inflammation of the liver. "The same polymorphism was found to be associated with Flucloxacillin-induced hepatitis, but it was attributed to its LD with nearby HLA-B genes (B*57:01 allele), which was in part consistent with our finding." (PMID 25789467, 2015).
hepatocellular carcinoma (2 papers, 2017 to 2024). A malignant tumor that arises from hepatocytes. "KIR3DS1 and HLA-B Bw4-Ile80 have been confirmed to protect chronic HCV patients from developing hepatocellular carcinoma." (PMID 29075265, 2017). "Enhanced expression of HLA-B by macrophages could potentially boost the CD8 T-cell-mediated attack on hepatocellular carcinoma (HCC) cells, thereby limiting tumor growth and promoting tumor containment." (PMID 39081317, 2024).
hyperthyroidism (2 papers, 2022 to 2023). Overactivity of the thyroid gland resulting in overproduction of thyroid hormone and increased metabolic rate. "Among these markers, HLA-B and HLA-DRW3 had been confirmed to be positively associated with hyperthyroidism, and HLA-D8 and HLA-DR3 had been confirmed to be positively associated with hypothyroidism." (PMID 36860870, 2023).
kidney damage (2 papers, 2012 to 2022). "HLA-A*2, HLA-A*11, and HLA-A*26 in the HLA class I regions have been related to the onset of IgAV, and HLA-B*44 and HLA-B*58 have been associated with kidney damage in IgAV patients." (PMID 35370802, 2022).
lymph node metastasis (2 papers, 2020 to 2024). "The lymph node metastasis AE in Tumour 3 acquired a missense mutation in HLA-B*40:02 with unknown functional impact." (PMID 31949146, 2020).
lymphoproliferative disorder (2 papers, 2024). "An important discovery is represented by the determination of the protective role of two HLA-B alleles, HLA-B*35:02 and HLA-B*81:01, for all patients with lymphoproliferative disorders, while we discovered that HLA-B*39:01 has a protective effect only against DLBCL." (PMID 38535155, 2024).
measles (2 papers, 2017 to 2018). A highly contagious viral infection caused by the measles virus. "This study also showed that HLA-B supertypes (B44, B58) were marginally associated with measles antibodies." (PMID 28158231, 2017).
Merkel cell carcinoma (2 papers, 2023 to 2025). "Moreover, our methodology reliably recapitulates findings from previous studies such as the loss of HLA-B expression in a Merkel-cell carcinoma case." (PMID 41229397, 2025).
metastatic tumor (2 papers, 2016 to 2021). "In addition, parametrium involvement was associated with complete as compared to partial loss of HLA-B/C (54 % vs. 31 %) and total classical HLA (54 % vs. 33 %) in the metastatic tumor cells (P = 0.037 and P = 0.050, Chi2 test – pairwise)." (PMID 27895918, 2016). "There is a significant reduction in the expression of the antigen presenting genes B2M, HLA-A, HLA-B, and HLA-C in the recurrent/metastatic tumors relative to the primary tumors." (PMID 33796222, 2021). "Decreased expression of HLA-A (SCC P < 0.001), HLA-B/C (SCC P < 0.01; AC P < 0.01) and total classical HLA (SCC P < 0.001; AC P = 0.02) was apparent in metastatic tumor cells compared to the primary tumor." (PMID 27895918, 2016).
migraine (2 papers, 2021 to 2025). "A recent biocomputational genetic association analysis of migraine and RA demonstrated that there is a phylogenetic relationship between the genes responsible for migraine and RA, such as SLC24A3 and HLA-B, MPPED2 and STAT4, and ATP1A2 and IL6R, respectively." (PMID 35281991, 2021).
mouth ulcers (2 papers, 2019 to 2023). "Within the HLA (chromosome 6p21) there was very strong evidence for association between rs2523589 (2.4 kb 5′ of HLA-B) and the odds of developing mouth ulcers (OR 0.94 per G allele, 95% CI: 0.93, 0.94; EAF 0.50; P = 1.6e−54)." (PMID 30837455, 2019).
Myelopathy (2 papers, 2010 to 2024). Myelopathy is an descriptive term, referring to pathology leading to a neurologic deficit related to the spinal cord. "Besides, two different studies have shown, the association of HLA-B*54 allele with a greater risk of developing myelopathy caused by type 1 human T-cell lymphotropic virus (HTLV-1)." (PMID 20927388, 2010).
myocarditis (2 papers, 2020 to 2025). Myocarditis is a condition that is characterized by inflammation of the heart muscle (myocardium). "We identified seven HLA alleles associated with the decreased frequency (risk) of clozapine-induced myocarditis (ORs < 1), including the HLA-B*07:02 allele (OR = 0.26, 95% CI: 0.07–0.98; P = 0.047)." (PMID 32066683, 2020). "In 9 patients with myositis complicated with myocarditis, the frequency of HLA-B*52:01 locus (16.7% vs. 3%) was higher than that in the normal population, and the difference was statistically significant (P = 0.018, OR = 6.467, 95% CI = 1.895–23.35)." (PMID 41357573, 2025). "In 9 patients with myositis and myocarditis, the frequency of HLA-B*52:01 locus was higher than that in the normal population." (PMID 41357573, 2025). "Studies have found that MHC class I-deficient non-obese diabetic mice carrying human HLA-DQ8 develop severe myocarditis and myositis after treatment with anti-PD-1 immune checkpoint inhibitors for cancer, however, HLA-B*52:01 has not been reported in myocarditis and myositis." (PMID 41357573, 2025).
non-Hodgkin lymphoma (2 papers, 2018 to 2020). Distinct from Hodgkin lymphoma both morphologically and biologically, non-Hodgkin lymphoma (NHL) is characterized by the absence of Reed-Sternberg cells, can occur at any age, and usually presents as a localized or generalized lymphadenopathy associated with fever and weight loss. "A US population-based case–control study showed that HLA-B*08 was independently associated with non-Hodgkin lymphoma (NHL) risk in whites." (PMID 30155344, 2018).